TTC8 (tetratricopeptide repeat domain 8)
Description:
The BBSome complex is thought to function as a coat complex required for sorting of specific membrane proteins to the primary cilia. The BBSome complex is required for ciliogenesis but is dispensable for centriolar satellite function. This ciliogenic function is mediated in part by the Rab8 GDP/GTP exchange factor, which localizes to the basal body and contacts the BBSome. Rab8(GTP) enters the primary cilium and promotes extension of the ciliary membrane. Firstly the BBSome associates with the ciliary membrane and binds to RAB3IP/Rabin8, the guanosyl exchange factor (GEF) for Rab8 and then the Rab8-GTP localizes to the cilium and promotes docking and fusion of carrier vesicles to the base of the ciliary membrane. The BBSome complex, together with the LTZL1, controls SMO ciliary trafficking and contributes to the sonic hedgehog (SHH) pathway regulation. Required for proper BBSome complex assembly and its ciliary localization.
Synonyms: BBS8; RP51
Tractability: Antibody: its Gene Ontology location is reachable by antibodies, with medium confidence. PROTAC: ubiquitination databases record sites on it.
Gene: Protein-coding gene on chromosome 14 (88,824,153 to 88,881,078, forward strand). Ensembl gene ENSG00000165533.
Subcellular location: Cytoplasm, cytoskeleton, microtubule organizing center, centrosome; Cell projection, cilium membrane; Cytoplasm; Cytoplasm, cytoskeleton, microtubule organizing center, centrosome, centriolar satellite; Cell projection, cilium
Subcellular location (Human Protein Atlas): Basal body; Nucleoli fibrillar center; Flagellar centriole; Perinuclear theca
Pathways (Reactome):
Organelle biogenesis and maintenance: BBSome-mediated cargo-targeting to cilium
Gene Ontology:
Molecular function: protein binding; RNA polymerase II-specific DNA-binding transcription factor binding
Biological process: establishment of anatomical structure orientation; cilium assembly; non-motile cilium assembly; sensory processing; anatomical structure morphogenesis; fat cell differentiation; sensory perception
Cellular component: BBSome; centrosome; ciliary basal body; ciliary membrane; cilium; cytoplasm; mitochondrion; cytosol; non-motile cilium; centriolar satellite; membrane; photoreceptor connecting cilium
Genetic constraint (gnomAD): Loss-of-function variants: 39 observed, 63.68 expected, observed/expected ratio (o/e) 0.61, 90% interval 0.47 to 0.8. The upper end of that interval is the gene's LOEUF score, 0.8, which puts it in group 3 of 6, group 1 being the genes least tolerant of losing a copy. Missense variants: 570 observed, 610.87 expected, observed/expected ratio (o/e) 0.93, 90% interval 0.87 to 1. Synonymous variants: 188 observed, 220.92 expected, observed/expected ratio (o/e) 0.85, 90% interval 0.75 to 0.96.
Homologues: Orthologues: chimpanzee TTC8 (98% identical), macaque TTC8 (98% identical), pig TTC8 (96% identical), dog TTC8 (96% identical), rabbit TTC8 (96% identical), guinea pig TTC8 (95% identical), mouse Ttc8 (94% identical), rat Ttc8 (94% identical), tropical clawed frog ttc8 (79% identical), Caenorhabditis elegans bbs-8 (40% identical), zebrafish ttc8 (39% identical), Drosophila melanogaster BBS8 (32% identical). Paralogues in human: TTC6 (20% identical), TTC13 (15% identical), CFAP70 (14% identical), TTC34 (13% identical), OGT (12% identical), TMTC1 (12% identical), TMTC2 (12% identical), TMTC3 (12% identical), TMTC4 (12% identical), TTC7B (11% identical), IFT88 (11% identical), BBS4 (10% identical), and 2 more.
Diseases named in the same sentence as TTC8 in open-access papers:
TTC8 is named in the same sentence as 22 diseases in open-access papers, as found by Europe PMC text mining. Sharing a sentence is not in itself a finding about the gene and the disease. The quoted sentences say what the papers report.
Bardet-Biedl syndrome (16 papers, 2012 to 2023). A ciliopathy with multisystem involvement. "BBS8 (TTC8) is a gene that has been associated with Bardet–Biedl syndrome and non-syndromic RP that codes for a BBSome member and is necessary for the proper trafficking of ciliary/outer segment proteins." (PMID 36830640, 2023). "A homozygous null BBS8 (TTC8) mutation leads to Bardet-Biedl syndrome (BBS) with randomization of left–right body axis symmetry, a known defect of the nodal cilium." (PMID 36273201, 2022). "In Bardet–Biedl syndrome, TTC8, BBS9, WDPCP, and IFT27 were shared by the two pipelines, and BBS4, BBS7, BBS12, and IFT74 suffered significantly different selective pressures between TG and BG birds." (PMID 35456484, 2022). "We focused on the alternative isoform usage of the Ttc8 gene in part because mutations in Ttc8 have been implicated in various ciliopathies including non-syndromic retinitis pigmentosa (RP) and in Bardet-Biedl syndrome (BBS, which commonly includes RP among its symptoms)." (PMID 27684375, 2016). "Two genes in the region have previously been associated with inherited retinopathies in humans; Spermatogenesis associated protein 7 (SPATA7) has been associated with juvenile RP and LCA, and tetratricopeptide repeat domain 8 (TTC8) with RP as well as Bardet-Biedl Syndrome (BBS)." (PMID 26401321, 2014).
ciliopathy (8 papers, 2015 to 2023). A genetic disorder of the cellular cilia or the cilia anchoring structures, the basal bodies, or of ciliary function. "Therefore, in this study, we analyze in-depth social behavior, as well as anxiety and cognitive functionality, in two ciliopathy mouse models, namely, the Bbs6/Mkks and Bbs8/Ttc8 knockout mice." (PMID 36498834, 2022).
retinitis pigmentosa (5 papers, 2011 to 2022). Retinitis pigmentosa (RP) is an inherited retinal dystrophy leading to progressive loss of the photoreceptors and retinal pigment epithelium and resulting in blindness usually after several decades. "Two of the genes (TTC8 and SPATA7) have been associated with Retinitis Pigmentosa (RP) in humans." (PMID 26401321, 2014). "It seems to take part in the same pathway as ACTN2, which in turn physically interacts with TTC8, often related to BBS and retinitis pigmentosa (Genemania)." (PMID 28800606, 2017).
Obesity (3 papers, 2019 to 2025). Accumulation of substantial excess body fat. "Taken together, the deletion in the canine TTC8 gene is associated with additional clinical features apart from PRA in the affected dogs, such as obesity, renal and genital anomalies, anosmia, short stature, and dental anomalies that are similar to human BBS." (PMID 32962042, 2020).
Anosmia (2 papers, 2020 to 2025). An inability to perceive odors. "Functional loss of the BBS8 gene (TTC8 protein) has been identified in Golden Retrievers with progressive retinal atrophy (PRA), concurrent with systemic symptoms such as weight gain and renal dysfunction, as well as a subjective assessment of anosmia." (PMID 40548244, 2025). "Interestingly, many of these mouse models, including the Ttc8 knockout mouse, also showed partial or complete anosmia." (PMID 32962042, 2020).
Anxiety (1 paper, 2022). Intense feelings of nervousness, tension, or panic often arise in response to interpersonal stresses. "Here, we extensively characterized the behavior of two rodent models of BBS, Bbs6/Mkks, and Bbs8/Ttc8 knockout mice concerning social behavior, anxiety, and cognitive abilities." (PMID 36498834, 2022).
cancer (3 papers, 2019 to 2025). A tumor composed of atypical neoplastic, often pleomorphic cells that invade other tissues. "These modules contained several cancer regulators such as Intraflagellar Transport (IFT) complex proteins (IFT74, IFT88), BBSome complex proteins (BBS2, BBS7, BBS9, BBS12), exocyst complex components (EXOC3, EXOC4, EXOC6B, EXOC7, and EXOC8), TTC8, TTC21B, EVC, and NEK1." (PMID 40700427, 2025).
TTC8 also shares sentences with these, for which no sentence is quoted: retinal degeneration (5 papers); Alström syndrome (2); Hydrocephalus (2); retinal ciliopathies (2); autosomal recessive cone rod dystrophy (1); Cognitive impairment (1); congenital nephrotic syndrome (1); head and neck squamous cell carcinoma (1); McKusick-Kaufman syndrome (1); polydactyly (1); renal dysfunction (1); Retinal atrophy (1); retinopathies (1); syndactyly (1); Usher syndrome (1).